GAS5 (growth arrest specific 5)
Diseases named in the same sentence as GAS5 in open-access papers (continued):
Sharing a sentence is not in itself a finding about the gene and the disease.
cancer (continued). "For several cancers, the suppression of GAS5 and mTOR expression has been shown to be reciprocal." (PMID 34202777, 2021). "Other lncRNAs such as HOTAIR, MALAT1, and GAS5 also show promise as cancer biomarkers." (PMID 33799946, 2021). "GAS5 is involved in the development of numerous diseases, especially cancer." (PMID 33391419, 2021). "Ranked No. 1 is GAS5, and the research in the literature shows that GAS5 may play a role in suppressing cancer." (PMID 33794766, 2021). "GAS5 is downregulated in different types of cancer and can regulate cancer cell behaviors, such as promoting cancer cell apoptosis and inducing cell proliferation, invasion and migration to promote cancer progression." (PMID 33308258, 2020). "Elevated GAS5 might present as a proto-oncogene in HCC, in contrast with its inhibitory role in other cancers, and subsequently could elevate the susceptibility to HCC." (PMID 32547314, 2020). "Cheng concluded that GAS5 could be a therapeutic target, while Li proposed that it could be used as a cancer marker." (PMID 33224198, 2020). "Furthermore, lncRNAs with cancer-associated SNPs, such as NEAT1, Gas5, or ANRIL have been linked to inflammation." (PMID 33329688, 2020). "The GAS5 gene is located at 1q25, a locus that displays dysregulation in several cancers." (PMID 31999937, 2020). "The growth arrest-specific transcript 5 (GAS5) is a >200-nt lncRNA molecule that regulates several cellular functions, including proliferation, apoptosis, invasion and metastasis, across different types of human cancers." (PMID 33076450, 2020). "The expression pattern and functions of GAS5 have only been investigated in cancer biology." (PMID 33308258, 2020). "As seen in other cancers, inhibition of Sox 2 decreased GAS5 expression." (PMID 31740660, 2019). "This shows that Hippo signal may be a new target for cancer chemotherapy, and GAS5 can inhibit the effect of miR-181c-5p on drug resistance." (PMID 30606744, 2019). "GAS5 was broadly found to be reduced in various cancer types, such as breast and lung cancer." (PMID 31847392, 2019). "Numerous studies indicated that expression of GAS5 was repressed in many types of malignant tumors." (PMID 31619268, 2019). "In our study, we found that GAS5 played a role in cancer promotion in CRC." (PMID 30902880, 2019). "GAS5 expression and its clinical implication have been examined in many types of cancers." (PMID 29416676, 2018). "GAS5 is well-known for the negative regulation of most cancer cells survival." (PMID 30693021, 2018). "Consequently, in steroid-driven cancer cells such as 22Rv1 cells, GAS5 function appears to be directly related to the SR-GAS5 signaling axis." (PMID 30037351, 2018). "Moreover, various studies have demonstrated a correlation between overexpression of lncRNA GAS5 through regulation of cell cycle, cell apoptosis, and promote cell death and cellular growth inhibition of different cancer cell lines." (PMID 29229673, 2018). "Recent studies hawe reported the role of GAS5 in many types of cancer." (PMID 30276165, 2018). "Similar to Tan-IIA, GAS5 itself is known for inhibiting cancer growth via apoptosis-induction." (PMID 30232236, 2018). "Numerous evidence links Gas5 dysregulation to human cancers." (PMID 29423063, 2018). "Further functional validation studies are warranted to confirm miR-34a/GAS5 interplay in cancer." (PMID 30289954, 2018). "A previous study illustrated that Gas5 was markedly downregulated in tissues, serum and cell lines of CRC patients, and negatively related to the cytokine expression in the mouse model of colitis-associated cancer." (PMID 29308053, 2018). "GAS5 produced piRNA from the snoRNA presents in its introns in human cancer cells." (PMID 30150632, 2018). "So far, it is well-established that GAS5 plays key roles in diverse molecular functions in cancers." (PMID 30693021, 2018). "Our results show that GAS5 was under-expressed in the three types of cancer; RCC, HCC and GB." (PMID 30289954, 2018).
cancer (continued). "The data highlights the role of GAS5 as a crucial cancer-suppressor in BC." (PMID 29445179, 2018). "This is further demonstrated by the presence of high levels of GAS5 in brain cells, which are considered the slowest dividing cells in the body as opposed to its lowest levels in other rapidly dividing cells, the most important of which are cancer cells." (PMID 30289954, 2018). "All these indicate that GAS5 can be a novel prognostic biomarker in unique cancer." (PMID 29163187, 2017). "A likely lncRNAs profile will include, among others, HOTAIR, MEG3, NEAT1, UCA1, and/or AK126698 in cancer-drugs cisplatinum-based therapies, and the recently proposed GAS5, UCA1, BC087858 and SOX2-OT involved in the gene-target therapies as EGFR-TKIs based oncological treatments." (PMID 28904641, 2017). "The results demonstrated that low expression of GAS5 could predict poor OS in cancer patients (HR = 1.955, 95% CI: 1.551–2.465, P < 0.001)." (PMID 29163187, 2017). "Over-expression of GAS5 in cancer cells inhibited cell proliferation." (PMID 29296179, 2017). "Increasing evidence revealed that abnormal expression of GAS5 is involved in many kinds of cancers." (PMID 29207621, 2017). "In conclusion, our meta-analysis found that lncRNA GAS5 could sever as a molecular biomarker to predict the prognosis of various cancers and the low GAS5 expression could indicate the poor prognosis." (PMID 29163187, 2017). "Our results showed that low expression levels of GAS5 could be a molecular biomarker of poor prognosis in cancer patients." (PMID 29163187, 2017). "Additionally, HOTAIR, MALAT1, H9 and GAS5 have been reported as prognostic markers in the plasma of cancer patients." (PMID 28872613, 2017). "In conclusion, this meta-analysis showed that GAS5 might be served as a novel biomarker for predicting prognosis in various types of cancers." (PMID 29163187, 2017). "Furthermore, our results suggest that low GAS5 expression is a risk factor for LNM and DM in diverse cancers." (PMID 29029523, 2017). "Indeed, down-regulation of GAS5 lncRNA levels attenuates apoptosis induction by a broad range of treatments; for most, cell death shows a direct quantitative relationship with GAS5 lncRNA levels in breast and other cancer cells." (PMID 26862727, 2016). "GAS5 is a tumor suppressor gene that is downregulated in various types of cancer." (PMID 25925741, 2015). "More crucially, for many cancers, low GAS5 lncRNA levels are predictive of poor prognosis." (PMID 26198250, 2015). "Low level of GAS5 indicates a poor prognosis in cancer patients." (PMID 25954300, 2015). "However, only 19 long noncoding RNAs from the LncRNADisease were found among the ESCALs, these including several lncRNAs such as HOTAIR, PVT1, H19 and GAS5 that have been reported to be dysregulated in multiple human cancers." (PMID 26158411, 2015). "Finally, the tumorigenic effect and migration abilities of the cancer cells were compared between GAS5, miR-103 and PTEN." (PMID 26511107, 2015). "GAS5 transcripts have also been shown to be important regulators of cell survival and apoptosis in human T-cells and breast and prostate cancer cell lines, and their overexpression sensitized mammalian cancer cell lines to inducers of apoptosis." (PMID 24926850, 2014). "GAS5 is also part of lncRNA abundantly expressed in cancer cells." (PMID 24885398, 2014). "Other ncRNAs have also been described as being involved in cancer cell survival, including PlncRNA-1, GAS5, HOTAIR, and several miRNA genes, which act by controlling apoptosis, the cell cycle, cell proliferation, or viability, through their interactions with intracellular signaling networks." (PMID 23130941, 2012). "The precise mechanism may be associated with the role of RBM38 and GAS5 in EGFR activation, c-Jun activation, autophagy, protein kinase B activation, formation of a hypoxic environment, dysregulation of apoptosis, cancer stem cell renewal, and epithelial–mesenchymal transition." (PMID 37296859, 2023).
cancer (continued). "By considering the close relationship between the activation of apoptosis and cancer therapy (i.e., radiotherapy and chemotherapy), the intracellular levels of GAS5 may have important implications for cancer therapy responses due to its apoptosis-promoting activity." (PMID 37444428, 2023). "Therefore, GAS5 overexpression in chemo-resistant cancer cells may be a potential strategy to improve the anti-cancer efficacy of drugs." (PMID 36672566, 2022). "Moreover, the relative level of GAS5 may be used as a useful prognostic marker to predict drug response or malignancy in cancer patients." (PMID 36672566, 2022). "Additionally, ectopic expression of GAS5 reduced the viability of HCT116R cells after treatment with various anti-cancer reagents such as doxorubicin (DOX), oxaliplatin (OXP), cisplatin (CDDP), and tamoxifen (TAM), which implies that GAS5 helps to improve drug response in resistant cells." (PMID 36672566, 2022). "Meanwhile, the potential role of GAS5 as an anti-cancer agent could be concluded in this study." (PMID 33976738, 2021). "Consequently, it seems that GAS5 can be considered as new player in cancer ontogenesis, progression and prognosis, as well as it may have prognostic and therapeutic applications in this disease." (PMID 33076450, 2020). "However, it seems that GAS5 is also involved in the therapeutic response of cancer patients." (PMID 33076450, 2020). "Thus, a decreased level of circulating GAS5 may be an indicator of better survival or treatment response in cancer." (PMID 32413995, 2020). "Oppositely, the inverse correlation between the two could also suggest that miR-34a inhibits GAS5, making its under-expression a cause of cancer rather than a result, as in the case of the miR-34a-GAS1 interaction." (PMID 30289954, 2018). "Although the expression pattern and possible functional role of lncRNA uc004cox. in tumorigenesis of cancer has not been totally elucidated, our work is the first study to report the importance of the uc004cox. expression profile, along with GAS5, in association with BC." (PMID 29516641, 2018). "Furthermore, the level of GAS5 was increased under the treatment of Gambogic acid (GA), a promising natural anti-cancer compound, whereas knockdown of GAS5 suppressed the inhibitory effect of GA on cell viability and abolished GA-induced apoptosis in T24 and EJ cells." (PMID 29445179, 2018). "Also, there is no sufficient research about the molecular functions of different transcripts of GAS5, which may play unique roles in cancers." (PMID 28771526, 2017). "Recent advances in our understanding of the cellular and molecular mechanisms of GAS5 lncRNA action will then be considered, before discussing how this knowledge may be harnessed clinically in the future for the improved diagnosis and treatment of cancer." (PMID 26198250, 2015). "Therefore, GAS5/CDK6 pathway may play an important role in regulating cancer development and progression." (PMID 24069260, 2013). "The mechanism involves GAS5 functioning as a ceRNA by sequestering miR-21, thus upregulating the expression of pro-apoptotic genes, including PDCD4, and sensitizing cancer cells to cisplatin treatment." (PMID 39958058, 2025). "In this study, we focus on the epigenetic regulation of four genes—ADIPOQ, GAS5, GATA4, and YAP1—selected for their established roles in fundamental cancer pathways and their potential for methylation-mediated dysregulation in TNBC." (PMID 41226688, 2025). "Gene therapy techniques can be employed to deliver functional copies of lncRNAs like growth arrest-specific 5 (GAS5) and MEG3 into cancer cells, thereby restoring their inhibitory effects on metastasis-related pathways." (PMID 39857631, 2024). "On the other hand, the lncRNA growth arrest-specific 5 (GAS5) acts as a tumor suppressor gene, inhibiting cancer cell proliferation, invasion, migration, epithelial-mesenchymal transition (EMT), and radioresistance." (PMID 39473440, 2024).
cancer (continued). "In melanoma cancer cells, GAS5 inhibits metastasis by reducing the expression of MMP-7 and 9, which are two important markers of cancer metastasis." (PMID 36770654, 2023). "LncRNAs have been shown to be expressed in all major cancer types, contribute to the hallmarks of cancer, and can act as oncogenes (“onco-lncRNAs”, such as HOTAIR, NEAT1 and MALAT1) or tumor suppressors (e.g. GAS5, MEG3, NBAT and LINC-PINT)." (PMID 37346034, 2023). "In particular, lncRNA GAS5, UNC5B-AS1, PARD6G-AS1, and LINC01060 have been widely reported in cancer and other diseases." (PMID 35360864, 2022). "GAS5 has been also shown to inhibit Calcium-Activated Chloride Channel 1 (CCLA1) expression and thus contributes to the suppression of cancer growth." (PMID 36685879, 2022). "Using the existing in vitro docetaxel sensitivity screening dataset (CTRPv2) and cancer cell line RNA-seq dataset (CCLE), we first assessed the correlation between the expression of GAS5 and the measured docetaxel sensitivity across 811 cancer cell lines." (PMID 34094978, 2021). "Contrary to these findings our study indicates that patients with lower GAS5 expression tend to have shorter durations of DFS, and OS, which would be more in line with the effect of low GAS5 expression in other cancers." (PMID 35054253, 2021). "We also investigated commonly shared lncRNAs between COAD and READ (CRCs) and found the presence of MAGI2-AS3, GAS5, SNHG1, KCNQ1OT1, SNHG20, and MIR17HG in both cancers." (PMID 35140741, 2021). "Growth arrest-specific transcript 5 (GAS5), a lncRNA that functions in embryogenesis, controls apoptosis and is downregulated in cancer." (PMID 33435206, 2021). "Some cancer-related lncRNAs (e.g., MALAT1, HOTAIR, GAS5, and lincRNA-p21) were found to be enriched in exosomes, suggesting that lncRNAs disseminate cell signals and alter the local cellular microenvironment via EVs." (PMID 33514011, 2021). "The lncRNAs such as NEAT1, lincRNA‐ROR, EFNA3, and GAS5 are HSF1 targets, which are all involved in cancer." (PMID 32691951, 2020). "Growth arrest specific 5 (GAS5), located in chromosome 1q25, is downregulated in many cancers and in HCC its expression levels inversely correlated with patient survival." (PMID 32429062, 2020). "To determine the enrichment of GAS5 in CC, we investigated the expression level of GAS5 in the TCGA database via GEPIA, which indicated a low level of GAS5 in cancer tissues compared to adjacent normal tissues." (PMID 32661236, 2020). "Equivalently, lncRNAs GAS5 and CAIF modulate ATG3 in certain pathological conditions such as osteosarcoma, myocardial infarction and cancer." (PMID 32489713, 2020). "Thirty-five cancer-relevant lncRNAs were identified, including the oncogenic lncRNAs MALAT1 and UCA1 and lncRNAs GAS5 and TUG1, which act as tumor suppressors." (PMID 33519750, 2020). "These lncRNAs can be either upregulated (e.g., ANRIL, SNHG12, NEAT1 in some cancers, PVT1) or downregulated (e.g., GAS5, NEAT1 in APL) in order to promote cell proliferation and migration, and prevent apoptosis of cancerous cells." (PMID 30654440, 2019). "Growth arrest-specific 5 (GAS5), an lncRNA plays an important role in regulating mammalian cell apoptosis and cell population growth, is frequently inhibited in many cancers." (PMID 31717266, 2019). "As expected, mTOR inhibition raises GAS5 levels, although Pickard and Williams (2014) found that both PI3K and mTOR inhibition are needed to elevate GAS5 levels in different cancer cell types in vitro." (PMID 31533355, 2019). "Growth arrest-specific transcript 5 (GAS5), a lncRNA, has been identified in the dysregulation of the cell cycle in several cancers." (PMID 31500396, 2019).
cancer (continued). "Here we selected six candidate cancer-related lncRNAs (ZFAS1, PRNCR1, GAS5, TUG1, linc-ROR, and H19) through articles that were previously reported to be dysregulated in cancer." (PMID 29559565, 2018). "Compared to GAS5 and ZFAS1, the role of miR-940 is less clear and appears to be different depending on the type of cancer." (PMID 29416676, 2018). "Consequently, we believe that GAS5 could potentially be used as a prognostic marker for cancer." (PMID 30289954, 2018). "In some pathological processes, such as cancer, the expression levels of lncRNAs are increased (e.g., HOTAIR) or decreased (e.g., Gas5)." (PMID 29423063, 2018). "Through searching the published literatures, six lncRNAs (ZFAS1, PRNCR1, GAS5, TUG1, linc-ROR, H19) which have been reported to be abnormally expressed in cancer were included in the present study." (PMID 29559565, 2018). "The lncRNAs such as MALAT1, GAS5, ANRIL, PVT1, CCAT2 and HOTAIR etc. were found to be novel promising biomarkers to predict a poor prognosis in human cancers." (PMID 28594897, 2017). "Several lncRNAs, such as HULC, HOTAIR, HOTTIP, GAS5, and HOST2, have been identified as miRNA targets in various cancers, and these findings provide further understanding of lncRNA regulation during tumorigenesis." (PMID 28492554, 2017). "The results showed that tens of lncRNAs, including cancer-related lncRNAs TUG1, DLEU2, and GAS5, were bound by at least two of the three RBPs at identical binding sites." (PMID 25642422, 2014). "This comprehensive analysis identified a batch of core lncRNAs that exhibited strong associations and high regulatory potential across multiple cancers, including NEAT1, MALAT1, GAS5, TP53TG1, and LINC00941, many of which have been previously confirmed to be closely related to cancer progression." (PMID 41373831, 2025). "Both GAS5 and MALAT1 have been extensively studied in the field of cancer research." (PMID 40331955, 2025). "GAS5 increases the level of FOXO1 by inhibiting miR-196a, thus suppressing cancer invasion." (PMID 39941145, 2025). "In addition, recent studies have reported that lncRNAs, such as GAS5, TRPM2-AS, OIP5-AS1 act as ceRNAs and microRNA sponges to promote the expression of target genes and consequently enhance radioresistance in several cancers 38-40." (PMID 37056929, 2023). "We found that GAS5 expression was downregulated in the MCF7 and MDA231 cancer cells." (PMID 35059460, 2022). "For instance, lncRNA GAS5 and CCAT2 have been indicated as sponges in promoting cancer development." (PMID 33393590, 2021). "A number of studies have demonstrated the role of CSC-related miRNAs/lncRNAs such as miR-1976, miR-196a-5p, miR-221, HOTAIR, and GAS5 in EMT, emphasizing on the multifaceted functions of these transcripts in the carcinogenesis and connection between these cancer-related processes." (PMID 34368145, 2021). "We first filtrated ER lncRNAs with continuous status in multiple cancers (EA samples/ES samples > 2 or <0.5 in at least three cancer types) and obtained six EA lncRNAs (PVT1, PSMD5-AS1, FAM83H-AS1, MIR4458HG, HCP5, and GAS5) and three ES lncRNAs (CTD-2201E18.3, HCG11, and AC016747.3)." (PMID 34222227, 2021). "In addition, non-coding host genes have recently been found to be involved in cancer onset or progression, for example ZFAS1, GAS5, and MEG8." (PMID 32046192, 2020). "The GAS5 transcription unit has been studied in cancer and non-cancer settings, such as hormonal signaling in normal tissues." (PMID 31533355, 2019). "The abundance of the selected mRNAs with various expression levels, as well as enhancer-associated RNAs and cancer biomarker long non-coding RNAs (MALAT1, GAS5 and TUG1), were not significantly different between the two groups as assessed by RT-qPCR." (PMID 30140372, 2018). "ROC curves showed no prognostic value for GAS5 nor miR-34a to predict survival of cancer patients in RCC and GB, or to predict CTP class for liver cell failure in HCC patients (p > 0.05)." (PMID 30289954, 2018).